RDX (radixin)
Description:
Probably plays a crucial role in the binding of the barbed end of actin filaments to the plasma membrane.
Synonyms: DFNB24
Tractability: Antibody: its Gene Ontology location is reachable by antibodies, with high confidence; UniProt places it where antibodies can reach, with medium confidence; the Human Protein Atlas places it where antibodies can reach. PROTAC: ubiquitination databases record sites on it; its protein half-life has been measured.
Target class: Structural protein
Gene: Protein-coding gene on chromosome 11 (109,864,295 to 110,296,712, reverse strand). Ensembl gene ENSG00000137710.
Subcellular location: Cell membrane; Cytoplasm, cytoskeleton; Cleavage furrow; Cell projection, microvillus; Cell projection, stereocilium
Subcellular location (Human Protein Atlas): Plasma membrane; Nucleoplasm
Pathways (Reactome):
Sensory Perception: Sensory processing of sound by inner hair cells of the cochlea; Sensory processing of sound by outer hair cells of the cochlea
Developmental Biology: Recycling pathway of L1
Gene Ontology:
Molecular function: actin binding; ATPase binding; cadherin binding; protein binding; RNA binding; cell adhesion molecule binding; protein kinase A binding; cytoskeletal protein binding; protein domain specific binding
Biological process: establishment of endothelial barrier; positive regulation of early endosome to late endosome transport; positive regulation of gene expression; positive regulation of protein catabolic process; positive regulation of protein localization to early endosome; protein localization to plasma membrane; regulation of adherens junction organization; regulation of organelle assembly; establishment of protein localization to plasma membrane; regulation of cell shape; regulation of Rap protein signal transduction; apical protein localization; barbed-end actin filament capping; cellular response to platelet-derived growth factor stimulus; cellular response to thyroid hormone stimulus; establishment of protein localization; positive regulation of G1/S transition of mitotic cell cycle; regulation of postsynaptic neurotransmitter receptor diffusion trapping
Cellular component: apical plasma membrane; cell periphery; extracellular exosome; extracellular region; focal adhesion; plasma membrane; adherens junction; apical part of cell; cortical actin cytoskeleton; filopodium; lamellipodium; microvillus; stereocilium base; cell tip; cleavage furrow; cytoskeleton; midbody; ruffle; stereocilium; T-tubule
Genetic constraint (gnomAD): Loss-of-function variants: 26 observed, 66.61 expected, observed/expected ratio (o/e) 0.39, 90% interval 0.28 to 0.54. The upper end of that interval is the gene's LOEUF score, 0.54, which puts it in group 2 of 6, group 1 being the genes least tolerant of losing a copy. Missense variants: 507 observed, 613.1 expected, observed/expected ratio (o/e) 0.83, 90% interval 0.77 to 0.89. Synonymous variants: 202 observed, 200.74 expected, observed/expected ratio (o/e) 1.01, 90% interval 0.9 to 1.13.
Gene-disease validity (ClinGen):
ClinGen rates the evidence that RDX causes each of these diseases.
nonsyndromic genetic hearing loss (autosomal recessive): Definitive.
Homologues: Orthologues: chimpanzee RDX (99% identical), macaque RDX (99% identical), dog RDX (99% identical), pig RDX (99% identical), guinea pig RDX (98% identical), mouse Rdx (98% identical), rat Rdx (98% identical), tropical clawed frog rdx (96% identical), rabbit RDX (93% identical), Drosophila melanogaster Moe (61% identical). Paralogues in human: MSN (81% identical), EZR (77% identical), NF2 (47% identical), FRMD4B (25% identical), FRMD4A (25% identical), ERMN (13% identical).
Diseases named in the same sentence as RDX in open-access papers:
RDX is named in the same sentence as 78 diseases in open-access papers, as found by Europe PMC text mining. Sharing a sentence is not in itself a finding about the gene and the disease. The quoted sentences say what the papers report.
breast carcinoma (28 papers, 2011 to 2024). "We then looked for correlations between NSC sensitivity and expression levels of ezrin and radixin in this panel of breast cancer cells." (PMID 36923551, 2022). "For example, adipokines such as LEP and RETN promote metastasis through activation of ezrin, radixin and moesin proteins in breast cancer cells." (PMID 36362348, 2022). "Radixin was expressed in most of the breast cancer cell lines, while moesin was only detected in MDA-MB-231 and MDA-MB-468 breast cancer cells, as well as MCF10A cells." (PMID 36923551, 2022). "Blocking the expression of RDX significantly inhibits breast cancer cell migration regulated by let-7b repression." (PMID 34157951, 2021). "Ezrin phosphorylation regulates the invasion and metastasis of breast cancer cells and pancreatic cancer cells, and radixin regulates cell migration and cell-cell adhesion in prostate cancer." (PMID 33833821, 2021). "We identified a juxtamembrane positively charged cluster responsible for the interaction of MT1-MMP with ERM (ezrin/radixin/moesin) cytoskeletal connectors in breast carcinoma cells." (PMID 32028690, 2020). "For instance, ezrin inhibition reduced metastatic spread of OS and breast cancer, while silencing moesin and radixin were shown to reduce migration and invasion of melanoma and colon cancer, respectively." (PMID 33005093, 2020). "Our previous studies in EVs shed from multidrug resistant breast cancer cells showed a selective packaging of Ezrin, Radixin, Moesin and CD44 in resistant breast cancer cell-derived EVs." (PMID 26938523, 2016). "In contrast to HeLa cells, SKBR3 cells showed no expression of moesin, and we therefore focused on the presumed role of ezrin and radixin in the regulation of ErbB2 receptors in this breast cancer cell line." (PMID 27029001, 2016). "Even though these effects seem to be specific to the inactivation of ezrin and radixin in breast cancer cells, it is likely that inactivation of ErbB-mediated signaling contributes only partially to this mechanism." (PMID 27029001, 2016). "Estrogens stimulate ER+ breast cancer cell movement through the ezrin–radixin–moesin family of actin regulatory proteins, inducing actin and cell membrane remodeling." (PMID 24904530, 2014). "In breast cancer and lung cancer, reduced expression of radixin has been found in tumor tissues compared with the adjacent benign tissues." (PMID 25136657, 2014). "miR-31 has been shown to be an inhibitor of breast cancer metastasis by targeting RhoA, RDX and ITGA which are involved in tumor motility, invasion and resistance to anoikis." (PMID 21483847, 2011). "Moreover, three top genes EZR (ranked 12th), TUBB (ranked 27th), and RDX (ranked 36th), were shown to be involved in organization and regulation of morphological characteristics of breast cancer cells including cell shape and membrane to membrane docking." (PMID 28133571, 2017). "Additionally, ceramide regulates actin cytoskeleton dynamics in breast cancer cells through modulation of ezrin, radixin, moesin function." (PMID 24872355, 2014). "However, regression analyses suggest a stronger correlation between ezrin levels and NSC sensitivity compared with radixin in breast cancer cells and that breast cancer cells may be more dependent on ezrin function over other ERMs." (PMID 36923551, 2022). "Additionally, miR-200b and miR-200c could suppress migration and invasion of breast cancer cells by regulating ezrin-radixin-moesin and fucosyltransferase-4." (PMID 31488193, 2019). "BRCA1 has previously been reported to interact with MSN/RDX through its BRCT domain, an interaction that localises the protein to the leading edges and focal adhesion sites in breast cancer cells." (PMID 39009827, 2024). "miR-31 decelerates breast cancer metastasis by targeting genes such as integrin α5 (ITGA5), radixin (RDX), and Ras homolog family member A (RhoA)." (PMID 35805066, 2022).
breast carcinoma (continued). "We used siRNA silencing of Ezrin, Radixin, Moesin and CD44 to evaluate the role of each protein in regulating P-gp function in drug-resistant breast cancer cells." (PMID 26938523, 2016). "It has been reported that miR-31 possessed multiple mechanisms to inhibit breast cancer metastasis by partial coordination to repress the metastasis-promoting genes, such as RhoA, ITGA5 and RDX." (PMID 27174918, 2016). "We show that, Radixin and CD44 are required for regulating P-gp drug efflux in resistant breast cancer cells at a functional level." (PMID 26938523, 2016). "Our previous studies in Dx-EVs showed a selective packaging of Ezrin, Radixin, Moesin and CD44 in resistant breast cancer cell-derived EVs." (PMID 26938523, 2016). "The miRNA let-7b-5p was also shown to have a tumor suppressor role in breast cancer patients with lymph node metastasis, by repressing the expressions of the genes PAK1, DIAPH2, RDX and ITGB8." (PMID 26763900, 2015). "miR-31, a well-known anti-metastatic miRNA in breast cancer, was first shown to inhibit breast cancer metastasis both in vitro and in vivo through the targeting of integrin-α5 (ITGA5), radixin (RDX) and RhoA and later through targeting of WAVE3." (PMID 25927669, 2014). "The silencing of the mRNA targets of miR-31, integrin-α5 (ITGA5), radixin (RDX), and RhoA, reduced local invasion and motility in vitro and decreased the development of metastases in a xenograft mouse model of breast cancer." (PMID 22550419, 2012). "Similarly, it is reported that radixin (RDX), a PANoptosis prognosis-related gene, is widely involved in signaling pathways such as immune response and cell proliferation in breast cancer." (PMID 38169587, 2024). "We observed the selective packaging of P-gp, CD44, Ezrin, Radixin, and Moesin in MDR breast cancer derived MPs together with 117 other proteins unique to the resistance cargo, which we proposed may play a role in establishing the MDR phenotype in cancer cell populations." (PMID 29062386, 2017). "This closely matches the values for total ezrin, but not total radixin, supporting the conclusion that ezrin expression and activation state correlates with NSC sensitivity in this panel of breast cancer cell lines." (PMID 36923551, 2022).
prostate carcinoma (11 papers, 2011 to 2024). A carcinoma that arises from epithelial cells of the prostate gland. "For example, Valderrama F found that silencing RDX by siRNA inhibited the migration of PC3 prostate cancer cells and increased the cell area and cell–cell contacts mediated by adherent junctions." (PMID 37759298, 2023). "PTCH1 and RDX are other 2 genes shared by our breast and prostate cancer cells, both are targeted by multiple miRNAs." (PMID 34157951, 2021). "In the non-type molecular subtype, TLN1 is significantly hyperphosphorylated at S425 in the head domain (band 4.1, ezrin, radixin, moesin homology domain), a site also known to be hyperphosphorylated in prostate cancer." (PMID 31108958, 2019). "In prostate cancer, circulating miR-409-3p functions as repressor of metastasis, with this miRNA binding to the 3′ untranslated region of the pro-metastatic gene radixin to suppress its expression." (PMID 31096984, 2019). "Potential miR-409-3p target genes have been previously reported; for example, Beclin-1 in colon cancer, radixin in gastric cancer, and Ras suppressor 1 and stromal antigen 2 in prostate cancer." (PMID 30846940, 2019). "According to this report, perturbation of radixin activity in the metastatic prostate cancer cell line PC3 by siRNA technology resulted in an elevated increase in spreading of cells, enhanced cell-cell adhesion and acquisition of epithelial phenotype." (PMID 26983550, 2016). "It is reported that radixin can regulate cell migration and cell-cell adhesion through Rac1 activation in prostate cancer cells." (PMID 25136657, 2014). "On the contrary, the expression of radixin is greatly increased in prostate cancer, colon cancer, pancreatic cancer, and gliomas, and elevated level of radixin is closely related to the poor prognosis of cancers." (PMID 25136657, 2014). "While the expression levels of two members of this family, radixin and moesin, have been studied in many tumor types, to our knowledge they have not been investigated in prostate cancer." (PMID 21235778, 2011).
gastric cancer (10 papers, 2014 to 2024). A primary or metastatic malignant neoplasm involving the stomach. "This included differentially methylated loci within the RDX gene, which encode a cytoskeletal component that has been shown to inhibit metastasis in gastric cancer." (PMID 27795744, 2016). "The results implicate that reducing the expression of radixin through modulators possesses possible therapeutic effects on gastric cancer." (PMID 39457653, 2024). "The knockdown of radixin also inhibits the metastasis of human gastric carcinoma cells in vitro by upregulating E-cadherin." (PMID 39457653, 2024). "Elevated miR-196a/-196b expression in gastric cancer reduced the expression of radixin, suggesting that miR-196a/-196b inhibitory oligonucleotides can be considered as a therapeutic potential in suppressing gastric cancer metastasis." (PMID 33171868, 2020). "Knockdown of radixin in gastric cancer increased cell adhesion and suppressed metastasis, by increasing the expression of E cadherin." (PMID 33171868, 2020). "Succinylation is reported to occur on ezrin Lys60, and a global proteome analysis for human gastric cancers also identified Lys438 in ezrin, human radixin Lys435, mouse radixin Lys83, and moesin Lys79 and Lys165." (PMID 31018575, 2019). "For instance, miR-409 promotes epithelial-to-mesenchymal transition and prostate tumorigenesis while it suppresses tumor cell invasion and metastasis by directly targeting radixin in gastric cancer." (PMID 30671387, 2018). "Experimental studies have revealed that radixin contributes to the invasion and metastasis of gastric cancer cells and glioma cells, and silencing of radixin inhibited the invasion and growth of pancreatic cancer cells in vitro and in vivo." (PMID 25136657, 2014). "miR-409 serves as a newly discovered manager in multiple types of cancer which directly targeting radixin to depress tumor cell metastasis and invasion in gastric cancer, also functions as a tumor suppressor in non-small-cell lung cancer (NSCLC) through PI3K/AKT pathway by directly targeting SPIN1." (PMID 32662828, 2020). "Targeting radixin may function to inhibit gastric cancer tumorigenicity and metastasis." (PMID 39457653, 2024). "In human gastric carcinoma cells that express all three ERM proteins, radixin knockdown reduced the expression of both MRP2 mRNA and protein, leading to a decrease of the efflux ability." (PMID 39457653, 2024). "In gastric cancer cells, ICAM2 decreased the expression of radixin." (PMID 39457653, 2024).
colon cancer (8 papers, 2014 to 2021). "RDX (encodes radixin) is overexpressed in many tumor tissues and was suggested to enhance colon cancer cell invasion." (PMID 31426369, 2019). "Together, our findings suggest that radixin enhances the invasion and migration of colon cancer cells." (PMID 25136657, 2014). "In summary, our present work demonstrates that radixin can promote the invasion of colon cancer cells by activating Rac1-ERK pathway and upregulating MMP-7 production." (PMID 25136657, 2014). "Our results showed that the expression of radixin was increased in colon cancer cells, further confirming a role of radixin in colon cancer." (PMID 25136657, 2014). "In the present study, we found that the expression of radixin was markedly elevated in colon cancer cells." (PMID 25136657, 2014). "The results showed that the invasion and migration abilities of radixin siRNA cells were significantly suppressed compared with control siRNA cells, suggesting that radixin can enhance the invasion and migration of colon cancer cells." (PMID 25136657, 2014). "Since radixin can regulate the activation of Rac1 and ERK1/2 and Rac1-ERK signaling is essential for the colon cancer cell invasion and migration, it is possible that radixin promotes the invasion and migration through activation of Rac1-ERK pathway." (PMID 25136657, 2014). "Further, we investigated the role of radixin in colon cancer cell invasion and migration and elucidated the possible molecular mechanism of radixin in regulating cell invasion." (PMID 25136657, 2014). "Moreover, radixin is found to be significantly increased in human colon tumor tissue and almost equally upregulated in various kinds of human CRC cell lines, such as NCM460, HT-29, Caco-2, HCT116, and LoVo cells." (PMID 34577564, 2021). "Moreover, abundant levels of radixin were detected in human colon tumor tissue and also in a variety of human colon cancer cell lines." (PMID 33974673, 2021). "So we here aimed to determine the function of radixin in colon cancer cell invasion." (PMID 25136657, 2014). "Finally, we identified that radixin promoted invasion and migration of colon cancer cells by activating Rac1-ERK pathway and by increasing MMP-7 production." (PMID 25136657, 2014). "In this study, we examined the expression of radixin in colon cancer cells." (PMID 25136657, 2014). "Interestingly, we found that the expression of radixin was significantly elevated in colon cancer cells." (PMID 25136657, 2014). "The expression level of radixin is found to be significantly increased in colon tumor tissues." (PMID 25136657, 2014). "Consistently, we found that radixin was necessary for the activation of Rac1 in colon cancer cells." (PMID 25136657, 2014). "Here, using invasion assay and migration assay, we found that knockdown of radixin by siRNA suppressed the invasion and migration of colon cancer cells, implicating that radixin may be a key mediator in the regulation of colon cancer cell invasion." (PMID 25136657, 2014). "Activation of Rac1-ERK pathway and consequent upregulation of MMP-7 production may contribute to the function of radixin in the regulation of colon cancer cell invasion." (PMID 25136657, 2014). "Knockdown of radixin suppressed the invasion and migration of colon cancer cells." (PMID 25136657, 2014). "Interestingly, we found that compared with NCM460 cells, the expression of radixin was markedly increased in all four colon cancer cells, indicating that radixin may act as an important player in colon cancer." (PMID 25136657, 2014). "However, little is known about the function of radixin in colon cancer." (PMID 25136657, 2014). "Thus, radixin may act as a novel target for the diagnosis and treatment of colon cancer." (PMID 25136657, 2014). "Therefore, radixin may act as a promising therapeutic target for the treatment of colon cancer." (PMID 25136657, 2014).
colon cancer (continued). "Since radixin can induce Rac1 and ERK1/2 activation these results suggest that radixin influences MMP-7 production via Rac1 and ERK1/2 activation in colon cancer cells." (PMID 25136657, 2014). "Using real-time PCR and western blotting, we detected the expression of radixin in nonmalignant human colonic epithelial NCM460 cells and colon cancer HT-29, Caco-2, HCT116, and LoVo cells." (PMID 25136657, 2014).